BMI1 (BMI1 proto-oncogene, polycomb ring finger)
Diseases named in the same sentence as BMI1 in open-access papers (continued):
Sharing a sentence is not in itself a finding about the gene and the disease.
cancer (594 papers, 2006 to 2026). A tumor composed of atypical neoplastic, often pleomorphic cells that invade other tissues. "BMI-1 (B-cell-specific Moloney murine leukemia virus integration site 1) has been implicated in both normal and cancer cell biology." (PMID 41455108, 2025). "BMI1 is an intracellular oncoprotein that is implicated in the initiation and progression of tumor-initiating cells across various cancer types." (PMID 39744574, 2025). "BMI1’s overexpression is associated with increased cell proliferation and the inhibition of apoptosis and differentiation, which are hallmark traits of cancer cells." (PMID 40221401, 2025). "Bmi-1 has been reported to cause carcinogenesis in an Ink4a–Arf-independent manner in various cancer types." (PMID 38141761, 2024). "The catalytic components of PRC1 such as RING1 A or B/BMI1 complex are associated with several cancers and correlate with poor prognosis, thus PRC1 represents an attractive therapeutic target for cancer." (PMID 36881608, 2023). "Compared to monolayer cultures, NB spheroids were characterized not only by significantly higher expression of a subgroup of CSC markers, including CXCR4, NANOG and BMI1, but also increased T389 phosphorylation of cancer-associated RNA-binding protein La." (PMID 36980635, 2023). "Amplification of the BMI1 gene or overexpression of BMI1-encoded proteins have been found in various cancer types." (PMID 36909198, 2023). "These large conglomerations of BMI1 proteins are known as “cancer-associated polycomb” bodies (CAP bodies)." (PMID 35110528, 2022). "As a core element of polycomb repressive complex 1(PRC1), BMI1 has been found to be associated with various human cancers and become an attractive therapeutic target." (PMID 36199791, 2022). "The association between CSCs and cancer-specific survival (CSS)/disease-specific survival (DSS) was found for Bmi1 only." (PMID 35743714, 2022). "BMI1 is an oncogene and its aberrant expression is associated with numerous cancers and resistance to certain chemotherapies, which confers poor prognosis." (PMID 34270461, 2021). "We also found that homozygous carriers of CCAT1 rs67085638 T were associated with increased BMI1 transcript levels and increased rapid growth compared to lower-grade tumour cells, spread of cancer cells to neighbouring tissues and lymph node metastasis." (PMID 34321511, 2021). "While stable miR-203 expression suppresses LASP1 and survivin, nanoliposomal delivery suppresses BMI1, indicating that suppression of distinct mRNA target profiles can lead to loss of cancer cell migration." (PMID 34449670, 2021). "The oncogene, BMI1 is associated with numerous cancers and resistance to certain chemotherapies when it is aberrant expression." (PMID 33927214, 2021). "BMI-1 represents a cancer stemness marker that is associated with the regulation of stem cell self-renewal." (PMID 34576269, 2021). "Since its discovery, BMI-1 has been implicated in several biological phenomena including development, cell cycle, DNA damage response, senescence, stem cell, self-renewal, and cancer." (PMID 33854168, 2021). "BMI1 is associated with self-renewal of cancer stem cells and sensitivity of tumors to chemoradiotherapy." (PMID 33927214, 2021). "While the current study delineates the impact of BMI1 on cell cycle progression and evasion of apoptosis, BMI1 has been implicated in multiple hallmarks of cancer, including DNA repair and self‐renewal." (PMID 33523558, 2021). "BMI1 is frequently up-regulated in a variety of cancer, and its over-expression is associated with poor prognosis." (PMID 34270461, 2021). "The carcinogenic features of BMI1 have linked BMI1 expression to cancer development and clinical prognosis of human tumors." (PMID 33302959, 2020). "Loss of BMI1 has been shown to induce growth arrest and cell death in cancer cells both in vitro and in vivo." (PMID 32343689, 2020).
cancer (continued). "Our findings contribute to a better understanding of BMI1-associated pharmacological cancer treatment strategies." (PMID 32343689, 2020). "Here, we performed a drug resistance screen on mutagenized human haploid HAP1 cells treated with BMI1 inhibitor PTC-318 to find new genetic and mechanistic features associated with BMI1-dependent cancer cell proliferation." (PMID 32343689, 2020). "B-cell-specific Moloney leukemia virus insertion site 1 (BMI1), a structural component of the polycomb repressive complex, is functionally associated with the self-renewal of cancer stem cells resulting in the chemo- and radiation resistance of tumors." (PMID 32726929, 2020). "In our study, both genetic and drug-induced BMI1 regulation decreased RNA expression of BCL-2, a known protein with anti-apoptotic functions, suggesting deregulation of both mitosis and cancer-associated survival mechanisms upon BMI1 inhibition." (PMID 32343689, 2020). "The emerging evidence has suggested that BMI1 acts as an oncogene in different cancers, and its overexpression is associated with poor outcomes in several human cancers." (PMID 32099526, 2020). "The mechanism underlying the anti-cancer activity of andrographolide involves the upregulation of miR-218 that directly regulates BMI1." (PMID 33066509, 2020). "Stemness of CSCs has been proved to be associated with massive cancer stem markers, such as Bmi1 and Sox2." (PMID 31119150, 2019). "B-cell specific Moloney murine leukemia virus integration site 1 (BMI-1) is implicated in self-renewal and maintenance of tumor-initiating cancer stem cells in various malignancies." (PMID 29983879, 2018). "Recently, Bmi-1 overexpression has been found in a variety of malignant tumors, and silence of Bmi-1 expression can cause apoptosis and senescence of tumor cells, suggesting an important role in tumor cell growth and survival." (PMID 29854278, 2018). "Of course, further investigations into mechanistic insights into PTC-209-induced Bmi1 loss in diverse cancers are still needed and warranted." (PMID 29200967, 2017). "Bmi-1 is a transcriptional repressor belonging to the polycomb group and is associated with cell proliferation and carcinogenesis in a variety of human cancers." (PMID 28424413, 2017). "Bmi1 has also been implicated in regulation of the PI3K/AKT pathways involved in cancer cell progression." (PMID 28418883, 2017). "Of the PRC1 subunits, BMI1 has been linked to the self-renewal of normal stem cells and the tumorigenic potential of cancer stem-like cells (CSCs)." (PMID 29050200, 2017). "In most of the cancer, BMI1 is associated with tumorogenesis and overexpression of BMI1 confers drug resistance." (PMID 28655885, 2017). "The molecular mechanisms underlying Bmi1's role in cancer progression are not completely understood." (PMID 26926789, 2016). "Third, knockdown of LITAF, previously identified as a downstream target of AMPK, upregulated Bmi-1, associated with increased cell viability, colony formation, and migration of cancer cells in vitro." (PMID 26717043, 2016). "In particular, BMI1 is up-regulated in cancer and associated with general aggressiveness and cancer stem cells (CSC)." (PMID 26623561, 2016). "BMI1 is an important physiological regulator, as its deregulation is associated with cancer, and adult stem cell depletion and accelerated ageing." (PMID 27105531, 2016). "The progression of Pten-loss initiated cancer originating in CARBs will be expected to be more rapid than in Bmi1-negative cells as Bmi1 overexpression has been shown to cooperate with Pten deficiency in promoting prostate tumorigenesis in transgenic mice." (PMID 27703144, 2016). "For example, FAL1 has been identified as an oncogenic lncRNA that associates with BMI1 and represses p21 expression in cancer by a functional genomic approach." (PMID 26336870, 2015). "BMI1 encodes a key regulator in several cellular processes, including normal stem cell renewal and cancer cell proliferation." (PMID 25978455, 2015).
cancer (continued). "BMI-1 is a key transcription factor that immortalizes human mucosal keratinoyctes, which is a hallmark of cancer cells." (PMID 24572994, 2014). "An 11-gene signature associated with the activated BMI1 was identified, and it reliably predicated shorter interval to recurrence and poor prognosis in 11 types of human cancers." (PMID 25526772, 2014). "Bmi-1 is oncogenic and has been associated with purported cancer stem cells and cell lines derived from head and neck squamous cell carcinoma 10,13,16,18–22." (PMID 24415717, 2014). "For example, co-expression of EZH2 and BMI1 was reported to be associated with poor prognosis in various cancers." (PMID 25243792, 2014). "Dysregulated expression of Bmi-1 has been found in various biological processes associated with cancer development and progression, including cell proliferation, invasion and repression of apoptosis or senescence." (PMID 23383216, 2013). "In addition, we found that three cancer cell stemness‐associated markers, Bmi1, CD133, and Sox2, were also expressed in the majority of B7‐H3 positive tumor cells in primary CRC samples from 48 patients." (PMID 40859957, 2025). "BMI1 overexpression has been tightly linked with cancer metastasis, invasion, and drug resistance." (PMID 36909198, 2023). "Indeed, the overexpression of BMI-1 is associated with cancer stemness, epithelial–mesenchymal transition (EMT) induction, chemoresistance and, thus, invasion, metastasis formation, and poor prognosis." (PMID 38275623, 2023). "Moreover, the inhibition of BMI1 is implicated as a potential therapeutic option for various cancers." (PMID 35261819, 2022). "Loss of Bmi1 causes apoptosis of human cancer cells 7 and stem cells." (PMID 35342358, 2022). "EMT is essential in cancer development and CSCs and Zeb1 have been implicated in the expression of several stem cell-associated transcription factors, including those with oncogenic potentials, such as BMI1, KLF4 and SOX2." (PMID 35404029, 2022). "BMI1 is also implicated in the self-renewal of cancer stem cells." (PMID 35563864, 2022). "The YB1 transcription factor induces the stemness-related gene expression and epithelial-mesenchymal transition in hepatocellular carcinoma while YY1 is associated with transcription factor (SOX2, OCT4, BMI1) expression in cancers suggesting a co-regulatory role in cancer stem cells." (PMID 33453053, 2021). "Moreover, BMI-1 is upregulated in many cancers and is associated with proliferation, invasion, metastasis, apoptosis, and malignant transformation in cancer cells." (PMID 34576269, 2021). "Moreover, upregulation of BMI-1 has been linked to tumor relapse, metastasis, and resistance to therapy in multiple human cancers." (PMID 34551814, 2021). "However, although BMI1 inhibition results in growth reduction and cell death of different cancer cell lines, the underlying mechanisms are often context-dependent and uncertain." (PMID 32343689, 2020). "BMI1 is an oncogene and can regulate the proliferating, apoptotic, and invasive abilities of cancer cells, which aberrant expression is linked with the carcinogenesis and chemoresistance of numerous cancers." (PMID 32581651, 2020). "Also, while BMI1 expression can cause resistance against different cancer treatment strategies, including chemotherapy or radiation, little is known about possible resistance-inducing responses to cell death resulting from BMI1 inhibition." (PMID 32343689, 2020). "In our experimental set-up, NUMA1-mutations strongly associated with cancer cell survival and may have an essential role–and hence serve as a potential biomarker–in resistance mechanisms in treatments associated with BMI1 inhibition." (PMID 32343689, 2020).
cancer (continued). "Biological variables associated to a high risk of progression included CIP2A levels, the expression levels of the polycomb group BMI1 gene, the activation of beta-catenin, specific gene signatures, and mutations in cancer-associated genes such as ASXL1, IKZF1, RUNX1, SETD1B, GATA2, MLL, and UBE2A." (PMID 31709190, 2019). "Moreover, RT-PCR analysis showed inhibition of the expressions of cancer stemness-associated BMI1 and CD44 genes, markers of stemness, when cancer cells were treated with BEP as compared to control." (PMID 30691094, 2019). "Bmi1 has been associated with cancer stem cell self-renewal and aggressive disease." (PMID 28418883, 2017). "BMI-1 has been implicated in a number of biological functions including development, cell cycle, DNA damage response, senescence, stem cell proliferation and self-renewal and cancer." (PMID 28968963, 2017). "Notably, BMI1 was identified based on its role in accelerating Myc-induced lymphomagenesis and has been linked to promoting self-renewal of cancer and leukemic stem cells." (PMID 29050200, 2017). "In carcinoma cells, BMI1 has also been linked to downregulation of the PTEN tumor suppressor." (PMID 29050200, 2017). "We assessed whether activation of AMPK exerts a causative effect on downregulation of Bmi-1 in cancer cells." (PMID 26717043, 2016). "The activation of stem cell-like programs during histone deacetylation is also associated with the expression of BMI-1, a member of the polycomb repressor complex 1 that is involved in chromatin remodeling and is highly expressed in cancer cells and cancer stem cells." (PMID 26742076, 2016). "Upregulation of BMI1 occurs in multiple cancer types and is associated with poor prognosis." (PMID 26633535, 2015). "Notably, BMI1 has been reported to be associated with the progression, recurrence, and chemoresistance of various types of cancer cells." (PMID 25726526, 2015). "Indeed, cytotoxic reagent CDDP not only enrich HNSCC CSCs by debulking proliferating cancer cell but also increase the fraction of stem cell by inducing putative self-renewal marker Bmi1 and associated with STAT3 activation." (PMID 26556875, 2015). "BMI1 is commonly upregulated in a variety of cancer types and associates with cancer evolution." (PMID 26425649, 2015). "One of the most studied pathways of Bmi-1 that is associated with cancer is the RB/E2F pathway." (PMID 26317630, 2015). "Bmi-1 overexpression has been demonstrated to induce epithelial-mesenchymal transition, to promote tumor metastasis and to cause radioresistance in cancer therapy." (PMID 24137328, 2013). "The underlying molecular mechanisms of Bmi1 function in cancer are not completely understood." (PMID 23437065, 2013). "Interestingly BMI1 is an oncogene involved in stem cell maintenance, and its over-expression leads to a loss of cell identity in multiple cancers." (PMID 23915344, 2013). "One may speculate that it is possible to stratify women in risk groups for development of malignant tumor in the breast, according to transcription level ratios of genes like Bmi-1 and Mel -18." (PMID 21162745, 2010). "Additionally, aberrant expression of BMI1 has been linked to cancer stem cell phenotype and oncogenesis." (PMID 20569464, 2010). "We therefore performed immunoflourescent co-staining for CTIP2 and BMI1 protein, in well, moderately and poorly differentiated HNSCC samples to see if some of the CTIP2 expressing cells also express the cancer stem cell (CSC) marker BMI1, previously implicated in self renewal and tumorigenesis." (PMID 19399189, 2009). "Therefore, we will also review Bmi-1-associated signaling pathways in other types of cancer here." (PMID 36726797, 2023). "Furthermore, the use of BMI1 non-expressing cell lines may be required to confirm the association between BMI1 and the anti-cancer effect of DSF/copper." (PMID 36362068, 2022).
cancer (continued). "Our findings suggest that the CCAT1 rs67085638 T allele elevating BMI1 expression might support increased rapid growth compared to lower-grade tumour cells and the expansion of cancer cells into the outer lining of the stomach or other organs and lymph node metastasis." (PMID 34321511, 2021). "The overexpression of Bmi1 in cancers could be caused by different mechanisms." (PMID 33014838, 2020). "However, Bmi1 has been shown to play a role in tumorigenesis in Ink4A-deficient models, suggesting that it may regulate other genes important in cancer." (PMID 25348805, 2014). "BMI-1 is considered to be a stem cell-related gene that is implicated in the tumorigenesis of head and neck tumors; its nuclear or cytoplasmatic expression could be related to the cancer stem cell phenotype in which it is expressed." (PMID 23031716, 2012). "On the other hand, upon chronic inflammation, metaplastic Paneth cells may represent source of activated Bmi1+ stem cells which, because of their increased proliferation rate, may acquire somatic mutations at oncogenes and tumor suppressors thus underlying cancer onset." (PMID 22745693, 2012). "However, whether re-expression of E-cadherin occurs in Bmi-1 overexpressing cancer cells in metastatic site, and if so, what is the underlying mechanism requires further investigation." (PMID 21276221, 2011). "In vitro, LCa/C@B markedly enhanced intracellular cisplatin accumulation, downregulated Bmi1 and cancer stem cell (CSC) markers, and restored chemosensitivity in HepG2/MDR cells." (PMID 41599624, 2025). "Our results showed that ALDH1, CD44, Sox2, Olig2, BMI1, LGR4, LGR5, Integrin α6, L1CAM, and ABC transporter associated with cancer stem cells were significantly downregulated." (PMID 39721005, 2025). "The current study explores the intricate relationship between Forkhead Box A1 (FOXA1) and B-cell-specific Moloney murine leukemia virus integration site 1 (BMI1) in the cancer progression and chemoresistance of NPC." (PMID 40623983, 2025). "Several studies have identified Bmi‐1 protein overexpression in various human cancers, including prostate cancer, lymphoma, multiple myeloma, and primary neuroblastoma, and it has been considered a marker of poor prognosis." (PMID 39791545, 2025). "This targeted strategy not only addresses the chemoresistance challenge in NPC but also heralds a promising avenue for improving patient outcomes, underscoring BMI1 as an innovative therapeutic target in the fight against drug resistance in cancer treatment." (PMID 40623983, 2025). "After receiving a small molecule inhibitor, the tumor’s volume was halved, providing strong evidence of the potential therapeutic benefit of Bmi-1 inhibitors in treating cancer." (PMID 39866230, 2025). "BMI1, a core subunit of polycomb repressive complex 1, acts as an oncogenic stem cell regulator and is frequently dysregulated in cancers." (PMID 41208974, 2025). "Lastly, isoTWAS identifies 52 genes (34 undetected by TWAS) that are associated with five or more cancer outcomes, including multiple known oncogenes or tumor suppressor genes, such as MYC, MUTYH, GNAI2, ACO2, and BMI1." (PMID 40775447, 2025). "BMi1 regulates chromatin structure by silencing crucial genes and maintains stemness in cancer cells." (PMID 40433700, 2025). "Current biological insights of Bmi-1 as a master regulator of stem cell self-renewal have emerged as a prominent player in cancer stem cell (CSC) biology." (PMID 39866230, 2025). "Cancer stem cells maintain stemness by regulating pluripotency genes, including Nanog, Sox2, and Bmi1, in response to Hh ligands secreted by neighboring stromal cells." (PMID 39352634, 2025). "The Bmi-1 inhibitor PTC028 has been shown to selectively inhibit the growth of cancer cells while protecting normal cells in an ovarian cancer model." (PMID 39866230, 2025).